BRAF (B-Raf proto-oncogene, serine/threonine kinase)
Diseases named in the same sentence as BRAF in open-access papers (continued):
Sharing a sentence is not in itself a finding about the gene and the disease.
colorectal cancer (continued). "Through a global miRNA expression analysis covering 760 miRNAs, they have identified 33 dysregulated miRNAs, all of which were up-regulated in BRAF-mutant colorectal cancer." (PMID 29115941, 2017). "This validation analysis successfully confirmed that miR-31 and miR-135b were significantly up-regulated, and miR-193a-3p was significantly down-regulated in BRAF-mutant colorectal cancers compared to KRAS/BRAF-wild-type cancers." (PMID 29115941, 2017). "It has been reported that KRAS and BRAF mutations were negatively correlated with the response to targeting EGFR treatment in lung and colorectal cancers." (PMID 28556791, 2017). "It was not until recently that the role of vitamin C has been of interest again after a preclinical mice study showed that high-dose vitamin C is selectively lethal to KRAS and BRAF mutant colorectal cancer cells by targeting the glutathione (GAPDH) pathway." (PMID 28791253, 2017). "Our result that miR-31 was one of the most up-regulated miRNA in BRAF-mutant colorectal cancers is consistent with their report." (PMID 29115941, 2017). "Focusing on a class of colorectal cancers with poor prognosis (those with a mutant form of the BRAF oncogene) they develop a mathematical model linking drug exposure, via cellular signal transduction, to tumor growth." (PMID 28649441, 2017). "We identified miR-193a-3p as a novel down-regulated miRNA in BRAF-mutant colorectal cancer, which offers more information on the significance of the dysregulation of multiple miRNAs in colorectal tumorigenesis of this molecular subtype." (PMID 29115941, 2017). "The purpose of this study was to identify miRNAs that were specifically dysregulated in human BRAF-mutant colorectal cancer, a molecular subtype of colorectal cancer with a higher malignant potential." (PMID 29115941, 2017). "When defined as markers with degree centrality at or above the 80th percentile in the colorectal cancer network, there were 11 hubs including methylation-related markers, MSI, BRAF mutation, and TIL in the proximal colon cancer network." (PMID 28623901, 2017). "Tumor response of patients with KRAS/BRAF-wild-type colorectal cancer who received anti-EGFR therapy based upon the miR-193a-3p expression status." (PMID 29115941, 2017). "In conclusion, we present novel evidence that miR-193a-3p is down-regulated in colorectal cancer, specifically BRAF-mutant colorectal cancer, and that miR-193a-3p acts as a tumor suppressor in colorectal cancer." (PMID 29115941, 2017). "Oncogenic mutations of RAS and BRAF activate the mitogen-activated protein kinase (MAPK) signaling pathway in 37% and 13% colorectal cancers, respectively." (PMID 27880935, 2017). "The role of vitamin C has been of interest again after a preclinical mice study showed that high-dose vitamin C is selectively lethal to KRAS and BRAF mutant colorectal cancer cells by targeting the glutathione pathway." (PMID 28791253, 2017). "In this system, the expression levels of miR-193a-3p were modestly but significantly decreased in SW48 and DiFi, both KRAS/BRAF-wild-type colorectal cancer cells." (PMID 29115941, 2017). "Following the MTD determination, three expansion cohorts of patients with biliary cancer, KRAS-mutant colorectal cancer, and BRAF-mutant colorectal cancer were enroled to further assess the safety and clinical activity of binimetinib." (PMID 28152546, 2017). "Currently, the most clinically significant mutated genes in colorectal cancer are KRAS, NRAS and BRAF as these genes provide information on a patients’ prognosis and their suitability for anti-EGFR therapies." (PMID 29029407, 2017). "This intermittent dosing regimen was chosen based on a previously published report that describes the effectiveness of these inhibitors on KRAS-mutant and BRAF-mutant non-small lung cancer and colorectal cancer lines." (PMID 28640835, 2017).
colorectal cancer (continued). "BRAF mutant colorectal cancers are resistant to kinase inhibition due to activation of EGFR caused by a BRAF-dependent negative feedback loop." (PMID 28891793, 2017). "Consistent with earlier studies, patients with a BRAF-mutant colorectal cancer had a poorer OS compared to those with a KRAS/BRAF-wild-type and KRAS-mutant cancer." (PMID 29115941, 2017). "To address this issue, we next examined the expression of miR-193a-3p in colorectal cancer cell lines with mutant BRAF protein overexpression." (PMID 29115941, 2017). "AZD8055, an mTORC1/2 inhibitor, reduces MCL-1 expression in KRAS- and BRAF-mutant colorectal cancer cells." (PMID 28659182, 2017). "Activating mutations in the KRAS and BRAF genes, leading to hyperactivation of the RAS/RAF/MAPK oncogenic signaling cascade, are common in patients with colorectal cancer (CRC)." (PMID 27999210, 2017). "We determined the prognostic value of BRAF and KRAS mutations in Korean colorectal cancer (CRC) patients." (PMID 28583095, 2017). "In this study cohort, we revealed that BRAF mutation was significantly associated with poorer DFS and OS in colorectal cancers." (PMID 28583095, 2017). "Collectively, our data suggest that KRAS‐ or BRAF‐mutant colorectal cancer lines are likely selectively dependent on Ras‐mediated RAD51‐dependent HRR signaling for survival." (PMID 28173629, 2017). "In colorectal carcinoma, BRAF amplification induced resistance to RAF/EGFR or RAF/MEK combinations through sustained MAPK pathway activity." (PMID 29312620, 2017). "Multiple studies have demonstrated that proportions of colorectal cancers with specific molecular features such as MSI, high-level CIMP, and BRAF and PIK3CA mutations gradually increase along the bowel subsites from rectum to ascending colon." (PMID 27391152, 2016). "Patients with obesity and patients with colorectal cancer of poor differentiation, lymph node metastasis, advanced TNM stage, MSI, KRAS, BRAF or PIK3CA mutations had shorter overall survival." (PMID 26515606, 2016). "It has been shown that human colorectal cancer cells carrying KRAS and BRAF mutations—giving them a highly glycolytic phenotype—can be selectively killed by high doses of vitamin C." (PMID 27616976, 2016). "Recently, a very efficient synergistic protocol of BRAF with autophagy inhibitors in colorectal cancer cells has been presented, as another example of the advantages and better efficiency of rational combined treatments as compared to mono-treatments." (PMID 27520705, 2016). "RAF inhibitor monotherapy is ineffective in BRAF-mutant colorectal cancer (CRC) but RAF inhibitor combinations have demonstrated improved efficacy, likely through superior suppression of MAPK signaling." (PMID 27308562, 2016). "Using a panel of BRAF V600E and WT colorectal cancer cell lines and in vitro selected resistant culture, and xenograft models, we demonstrate here that BRAFV600E confers resistance to mTOR inhibitors." (PMID 27351224, 2016). "It has been reported recently that KRAS and BRAF mutations were negatively correlated with the response to targeting EGFR treatment in lung and colorectal cancers." (PMID 26909593, 2016). "Based on the ineffectiveness of BRAFV600E inhibitors in BRAFV600E bearing colorectal tumors, the BRAF related autophagic properties in colorectal cancer cells are further exploited, by novel combinatorial anti-cancer protocols." (PMID 26802026, 2016). "We found striking similarities between colorectal cancers and adenomas during the evaluation of KRAS and BRAF mutations." (PMID 26910894, 2016). "In this study, 4302 patients with at least one colorectal polyp from a large colorectal cancer screening program were evaluated and genetic mutations in either KRAS or BRAF were detected in 495 patients." (PMID 26910894, 2016).
colorectal cancer (continued). "We focussed our study on colorectal carcinoma cell lines, because approximately 50% of colorectal tumors contain a mutated KRAS gene, and further 10% harbor mutated BRAF." (PMID 26799289, 2016). "The EGFR/HER2/KRAS/BRAF signaling pathway has been reported in pancreatic cancer and colorectal cancer other than in ovarian cancer." (PMID 26490766, 2015). "An oncogenic missense mutation p.V600E in BRAF, a downstream signalling molecule of KRAS, has been identified in around 5% of colorectal cancer tumors, though somewhat higher in this series at 10%, and results in activation of the MAPK signalling pathway." (PMID 25568935, 2015). "We used medical subject headings, including colorectal cancer, molecular genetics, KRAS and BRAF mutations, screening, survival, epidemiologic study, and Iran." (PMID 25685149, 2015). "Thirty-three patients ≤40 years with diagnosis of colorectal cancer and 41 patients with disease at >60 years of age were investigated for MSI, Mismatch Repair proteins expression, KRAS and BRAF mutations, hypermethylation, and LINE-1 hypomethylation." (PMID 26557847, 2015). "In order to compare two PCR based mutation detection methods, a total of 99 colorectal cancer samples were tested for KRAS and/or BRAF status by castPCR and Therascreen." (PMID 25568935, 2015). "Previous studies have clearly shown that patients with BRAF mutant colorectal cancer (CRC) receiving adjuvant chemotherapy following resection have a worse outcome compared to their BRAF wild type counterparts." (PMID 26097884, 2015). "Previous studies reported that BRAF, KRAS, and NRAS mutations occur in 10%–15%, 35–40%, and 2–7% of colorectal cancers, respectively." (PMID 26090613, 2015). "Vemurafenib, a BRAF inhibitor, reduced pS-EphA2 in cells harbouring BRAF mutation, but rather increased pS-EphA2 in NRAS-mutated SK-MEL-2 cells as well as in KRAS-mutated DLD-1 human colorectal cancer cells." (PMID 26158630, 2015). "The association with these features is well explained by the overlap of BRAF mutations with microsatellite instability (MSI-H), a common finding in the serrated pathway of colorectal cancer." (PMID 26299805, 2015). "A third combination of targeted inhibitors are BRAF and EGFR inhibitors in BRAF-mutant colorectal cancer." (PMID 26018524, 2015). "BRAF mutant colorectal cancer carries a poor prognosis which is thought to be related to poor response to conventional chemotherapy." (PMID 26097884, 2015). "In view of the role of RALA in RAS-induced tumorigenesis in human cells and particularly its involvement in colorectal cancer, we investigated the role of RALA in colorectal cancer cell lines carrying KRAS mutations in codon 12, 13 or the BRAF V600E mutation." (PMID 26033452, 2015). "The BRAF, KRAS, and NRAS mutations are widely recognized to be the major causes of RAS/RAF/MEK/ERK pathway dysregulation in colorectal cancer." (PMID 26090613, 2015). "As a consequence, BRAF V600E analysis is used to differentiate sporadic MSI colorectal cancers from Lynch syndrome cases." (PMID 25983749, 2015). "The aim of this study was to evaluate the prognostic role of MMR status, BRAF mutations and specific KRAS point mutation in 762 patients in Chinese population, and several clinicopathologic features to better stratify colorectal cancer patients." (PMID 25929517, 2015). "Frequency and percentage of KRAS and BRAF mutations in normal (N), low-grade dysplasia (LGD), high-grade dysplasia (HGD) and colorectal cancer (CRC) samples." (PMID 26291085, 2015).
colorectal cancer (continued). "In the present study, we were able to detect KRAS, BRAF, CD133 and PLS3 mutations in cell suspension enriched for all CTCs populations and in the corresponding primary tumor of 52 patients with colorectal cancer." (PMID 25902072, 2015). "In a study of 524 patients with BRAF mutant and wild-type BRAF colorectal cancer, the survival for the first group was 10.4 months, while that for the second group was 34.7 months." (PMID 25932044, 2015). "A patient with colorectal cancer with wt BRAF and wt KRAS in the primary tumor, who received a cetuximab-based combination for nearly one year had an emergence of a low frequency BRAF V600K mutation in cfDNA (0.02%)." (PMID 25980577, 2015). "In particular, both BRAF and KRAS mutations have been linked to CIMP status (high and low, respectively) in colorectal cancer." (PMID 25960768, 2015). "RALA activity was also detectable in HT29 colorectal cancer cells, which are KRAS wild-type and carry a BRAF V600E mutation." (PMID 26033452, 2015). "Primary samples from 762 colorectal carcinoma patients were analyzed for KRAS, BRAF gene mutations and MMR status." (PMID 25929517, 2015). "Mutations in genes such as KRAS, NRAS, BRAF and PIK3CA have become an important part of colorectal carcinoma evaluation." (PMID 26691448, 2015). "The study reported that HER-2 gene amplification was observed in 26.3% of KRAS and v-raf murine sarcoma viral oncogene homolog B (BRAF) wild type colorectal carcinomas in Spanish patients." (PMID 25452770, 2015). "BRAF inhibitors have been largely ineffective in BRAF-mutant colorectal cancer, MEK inhibitors have had little impact in a variety of RAS-mutated tumors, and PI3K inhibitors have yielded disappointing results in tumors harboring alterations in PTEN and PI3Kα." (PMID 24810962, 2014). "In this study we evaluated KRAS and BRAF status in 159 colorectal cancer samples obtained from the University of Tirana." (PMID 25267307, 2014). "Several mutational landmarks have been described in the progression to colorectal cancer, such as KRAS, BRAF and PI3K mutations, and were analyzed in our samples." (PMID 24516561, 2014). "For this study, we established an in vitro BRAF model system ideally suited for pharmacogenetic analyses by recombination of either V600E or wild-type BRAF in the colorectal cancer cell line RKO." (PMID 24885690, 2014). "In colorectal cancers, methylation of LOX have been correlated with higher microsatellite instability and BRAF-mutation, while in gastric cancer, it has been associated with tumor stage." (PMID 24626295, 2014). "The human colorectal cancer cell line DiFi, which harbors wild-type alleles of KRAS, BRAF, and PI3K, is highly sensitive to cetuximab." (PMID 25474137, 2014). "In one Phase I study, colorectal cancer patients underwent prospective molecular profiling for mutations in KRAS, BRAF, PIK3CA and expression levels of PTEN and pMET." (PMID 25401499, 2014). "The BRAF (V600E) mutation in colorectal cancers that are microsatellite stable (MSS) confers a poor patient prognosis, whereas BRAF mutant microsatellite-unstable (MSI) colorectal cancers have an excellent prognosis." (PMID 24651849, 2014). "Of the 757 cases analyzed for BRAF status, BRAF mutations were observed in nineteen cases and the incidence of BRAF in Saudi colorectal cancer was 2.5%( 19/757)." (PMID 25005754, 2014). "Mutations in KRAS, BRAF and PIK3CA are the most common somatic alterations found in the colorectal cancer (CRC) patients from Western countries; but their prevalence and prognostic value have not been adequately assessed in Asian patients." (PMID 25367198, 2014). "As current clinical practices in colorectal cancer revolve around KRAS, NRAS, and BRAF mutation status, diagnostic sequencing of either primary or metastatic tissue as available is acceptable for most patients." (PMID 25164765, 2014).
colorectal cancer (continued). "Methylation levels were correlated with MSI and CIMP statuses and known mutations within the APC, BRAF and KRAS genes in 264 matched samples representing the progression from normal to pre-invasive adenoma to colorectal carcinoma." (PMID 25432628, 2014). "Accordingly, HDC9 KRAS/BRAF wild-type colorectal carcinoma cells - that weakly express Abi1 - display high levels of E-cadherin and no cleavage of Laminin5 indicated by a single y2′ band migrating at 100–105 kD." (PMID 24913355, 2014). "A case in point is the EGFR-mediated reactivation of MAPK signaling, which contributes to the insensitivity of BRAF-mutant colorectal carcinomas to RAF inhibition with Vemurafenib." (PMID 25409462, 2014). "The vast majority of ITACs resembled colorectal cancer, showing deregulation of KRAS/BRAF genes that are involved in the early phases of colorectal cancer development." (PMID 23459231, 2013). "In colorectal cancer, KRAS and BRAF mutations have been shown to identify a cluster of patients that does not respond to anti-EGFR therapies; the identification of these mutations is therefore clinically extremely important." (PMID 23536897, 2013). "Several molecular classifications of colorectal cancer based on features such as chromosomal instability, point mutations (APC, KRAS, BRAF), microsatellite instability (MSI), and CpG island methylation have been proposed." (PMID 24130965, 2013). "The mutation status of the BRAF and KRAS genes has been proposed as prognostic biomarker in colorectal cancer." (PMID 24073892, 2013). "Molecular classification of colorectal cancer (CRC) is currently based on microsatellite instability (MSI), KRAS or BRAF mutation and, occasionally, chromosomal instability (CIN)." (PMID 23165447, 2013). "Our study confirms published data on the prognostic/predictive significance of BRAF, KRAS mutations and on the tumour expression of AREG, EREG mRNA in cetuximab-treated patients with colorectal cancer." (PMID 23374602, 2013). "BRAF V600E mutated colorectal cancer on the contrary, seems to display an innate resistance to inhibition with BRAF inhibitors, which was also demonstrated in colorectal cancer cell lines." (PMID 24298448, 2013). "A study has shown that BRAF amplified colorectal cancer cells acquired resistance to the MEK1/2 inhibitors selumetinib." (PMID 23078675, 2012). "Published analyses in colorectal cancer patients indicated that the mutational status of some molecular determinants such as K-RAS and BRAF is almost completely unaltered from primary to corresponding metastases." (PMID 22490361, 2012). "Treatment of vemurafenib-resistant BRAF-mutant colorectal cancer cells with an Akt inhibitor (MK-2206) overcame their resistance to vemurafenib." (PMID 23085539, 2012). "Mutation of BRAF and KRAS can result in aberrant c-Myc and SIRT1 protein deacetylase expression in the colorectal cancer." (PMID 23455493, 2012). "The most frequent mutations observed in colorectal cancer patients are found at codons 12 and 13 of KRAS, in approximately 35% of the patients, and the V600E mutation of BRAF, found in about 15% of the cases." (PMID 23207070, 2012). "The results were modest when compared to melanoma but clearly indicate that targeting mutant BRAF is a therapeutic option in colorectal cancer." (PMID 23097702, 2012). "In fact, over activation and crosstalk of parallel pathways like phosphatidylinositol 3-kinase (PI3 kinase) – AKT with MAPK in colorectal cancer is playing a main role in the observed different response to BRAF inhibitor treatments in colorectal cancer." (PMID 23056577, 2012). "Serrated pathway syndrome is a familial colorectal cancer that is predominantly BRAF mutant, in contrast to Lynch syndrome." (PMID 22792460, 2012).